SOX2 (SRY-box transcription factor 2)
Diseases named in the same sentence as SOX2 in open-access papers (continued):
Sharing a sentence is not in itself a finding about the gene and the disease.
cancer (continued). "Results of “ChEA 2016” analysis for 96 ≪stemness genes≫ showing elevated expression in TAMRA+ Krebs-2 carcinoma cells relative to TAMRA− cells, with regard to enrichment with SOX2/OCT4/POU5F1/NANOG/KLF4/c-MYC binding sites." (PMID 30505319, 2018). "The Sox2 gene is amplified and/or its expression is increased in lung and esophageal squamous cell carcinoma (SSC), identifying it as an oncogene for these cancers." (PMID 28191771, 2017). "These exosomes are also able to transfer their cargo into target cancer cells, inducing a dose-dependent increase in SOX2, OCT4 and Nanog proteins, leading to a dose-dependent decrease of cancer cell growth and tumorigenicity." (PMID 28068409, 2017). "TM4SF4 knockdown weakened sphere forming and suppressed the expression of cancer stem cell markers such as ALDH1A1, ALDH1A3, Oct3/4, Sox2." (PMID 29254164, 2017). "CHIR99021 also decreased typical stem cell markers, such as Sox2 and Oct3/4 and reduced OPN and clearly suppressed the metastatic and self-renewal capacity of cancer cells." (PMID 29254164, 2017). "GLI1 has also been shown to exhibit cancer stem cell property by overexpressing stem cell markers like OCT4, Nanog and Sox2." (PMID 28380428, 2017). "Our results showed down regulation of cancer stem cell markers such as OCT4, Nanog and Sox2 by penfluridol treatment." (PMID 28380428, 2017). "In breast lines and primary cancer culture, VEGFA rapidly upregulates SOX2 expression, leading to SNAI2 induction, EMT, increased invasion and metastasis." (PMID 28504716, 2017). "In the present study, we evaluated the expression of four cancer stem cell markers CD44, CD133, SOX2, Nanog in a large cohort of palatal MEC patients and identified some effective combinations of markers that have prognostic value for palatal MEC patients." (PMID 28262804, 2017). "The surface markers of cancer stem cells include CD133, CD44, Oct4, SOX2, Nanog, ALDH1, Bmi-1 and so on25." (PMID 28262804, 2017). "In ovarian cancer, coculture with MDSCs stimulates the expression of miR-101 in cancer cells, which regulates CtBP2 to control the expression of stemness genes, such as NANOG, OCT-4, and SOX-2." (PMID 28337221, 2017). "Altogether, cisplatin enriches cancer stem cells properties in SP fraction, which is evident from increased levels of pluripotency gene OCT4/SOX2/NANOG expression." (PMID 29169370, 2017). "In general, all those factors required for reprogramming cells, like POU3F2 (OCT7), Sox2, Sall2 and Olig2 are highly expressed in GBM and in more than 50% of cancers presenting high expression of these four transcription factors also CD133 is expressed." (PMID 29261132, 2017). "Using RT-qPCR analyses, we observed that SOX2 and OCT4 transcripts were dose-dependently and significantly increased in both cancer cell lines following treatments with hESCs-Exo." (PMID 28068409, 2017). "Many stem-like cells commonly overexpress markers such as NANOG, OCT-4, SOX-2, KLF-4 and C-MYC, where these genes play important roles in the regulation of self-renewal and tumorigenicity in CSC populations of several cancer types." (PMID 29069808, 2017). "Indeed, amount of studies have highlighted the central roles of SOX2 in maintaining stemness or cellular plasticity in cancer cells, in particular, it has been reported that SOX2 could be regulated by MAPK signaling for maintaining side population or CSCs in human NMIBC." (PMID 28182001, 2017). "Treated EWS cells analyzed for standard embryonic and cancer stem cell markers, Nanog, Oct-4, Sox-2, ALDH1A, and c-myc, showed significant reduction in these genes, indicating a decrease in cancer stem-like cell population." (PMID 29100387, 2017). "In fact, the pluripotent cell markers OCT4, SOX2, Klf4 and NANOG have been shown to be expressed in certain cancer cell types and to play an important role in oncogenesis." (PMID 28103575, 2017).
cancer (continued). "As the Sox2/Oct4 also modulate the EMT of OSCC, the regulation of the Sox2/Oct4 by miR-145 that modulate EMT and cancer stemness needs to be further investigated." (PMID 27557511, 2016). "The Cancer Atlas feature was interrogated to assess the antibody staining of YY1, SOX2, OCT4, NANOG and BMI1 in different cancer types." (PMID 27225481, 2016). "As already mentioned, certain phenotypic characteristics are shared by ES cells and some aggressive cancer cells, such as unlimited self-renewal and expression of some pluripotent genes (NANOG, OCT4, SOX2)." (PMID 27460364, 2016). "The neurospheres showed characteristics consistent with GICs: namely, neurosphere formation, expression of neural and/or cancer stem cell markers CD133 and Nestin and expression of core stemness factors Sox2, OCT4 and Nanog." (PMID 27119230, 2016). "To further explore the relationship between FGFR1 signaling and cancer stem cell traits, we measured the mRNA levels of stem cells markers CD133, NANOG, OCT4 and SOX2, when FGFR1 signals were activated by bFGF, and in the presence of FGFR1 inhibitor." (PMID 26936993, 2016). "Hypoxia can induce stem cell markers such as octamer-binding transcription factor 4 (OCT4), NANOG, SOX2, kruppel-like factor 4 (KLF4), c-MYC, and microRNA-302 in 11 cancer cell lines including HCC cells through hypoxia-inducible factor (HIF)." (PMID 27050147, 2016). "However, the transcription factors of SOX2 in cancer cells have remained unknown." (PMID 27418136, 2016). "However, whether NOTCH activation could stimulate SOX2 in cancer cells is still unknown." (PMID 27029061, 2016). "Hierarchical Cluster data suggests a much more complex situation of NOTCH1 and HES1 expression correlated with cancer stem cell marker CD44, ALDH1, Slug and SOX2." (PMID 27108536, 2016). "Recently, it was reported that NANOG plays an essential role in adult cell reprogramming, malignant cell transformation and cancer initiation, while OCT4 and SOX2 are dispensable; however, these reports did not distinguish between NANOG1 and NANOGP8." (PMID 28033430, 2016). "In order to identify highly consensus SOX2 downstream genes in lung SCC cells, we investigated genes previously reported to be regulated by SOX2 in multiple cancer cell lines." (PMID 26846300, 2016). "Cancer stemness markers such as OCT4 and SOX2 were highly expressed in MCF-7-ADR cells in sphere status." (PMID 26895471, 2016). "A close association was revealed between the frequency of expressions of YY1 and SOX2 as well as SOX2 and OCT4 in all cancers analyzed." (PMID 27225481, 2016). "Lastly, all the 13 NED areas in our sample collection were marked by distinct to strong SOX2 expression, and 11/13 also showed a distinct to strong NOTCH1 expression, involving nearly all cancer cells." (PMID 25686823, 2015). "Those segments contain well-known oncogenes, including EGFR, SOX2, and ERBB2, which are registered in the Cancer Gene Census database as amplified genes in several types of cancer." (PMID 26465158, 2015). "A statistically significant correlation coefficient between SOX2 and SOX2OT in cancer tissues, suggested the possibility of SOX2OT role in the regulation of SOX2 expression." (PMID 26136768, 2015). "Several miRNAs have been demonstrated to regulate stemness factors such as OCT4, NANOG, SOX2 and KLF4 in cancer cells, thereby modulating the proliferation, apoptosis, differentiation, drug resistance and immunity of cancer cells." (PMID 25603874, 2015). "Our results showed that reprogramming factors such as OCT4, SOX2, NANOG, LIN28 and miR-302a were upregulated significantly in 3D-cultured cancer cells compared with their monolayer counterparts." (PMID 25883172, 2015). "Embryonic stem cells rapidly progress through the cell cycle without checkpoints, and many components of the core embryonic stem cell machinery – SOX2, OCT4, NANOG, and c-Myc – are expressed and active in cancer stem cells." (PMID 25938542, 2015).
cancer (continued). "We have previously reported that introduction of NS into TERT-immortalized fibroblast and cancer cells resulted in the significant increase of the expression of MYC, OCT4 and SOX2." (PMID 25569094, 2015). "While the transcription factors SOX2 and OCT4 are increasingly reported to contribute to cancer progression through their functional control of cell self-renewal and the pluripotent state." (PMID 25906747, 2015). "Here we report that a new compound DC120 selectively targeted NPC cancer stem-like SP cells and sensitized NPC cells to conventional chemotherapy in vitro and in vivo by blocking the AKT signaling pathway and inhibiting Sox2 expression." (PMID 25749514, 2015). "This study was conducted to explore the function and role of SOX2 in EMT, a crucial step in cancer metastasis." (PMID 26370982, 2015). "Whereas our study showed that in ESCC, SOX2 exerted a regulatory action upstream of STAT3/HIF-1α, another report indicated the action of SOX2 downstream of HIF-1α in cancer cells other than ESCC." (PMID 26370982, 2015). "RT-PCR analysis further revealed that cancer cells upregulate several CSC markers upon co-culture with ADSCs, including SOX2, NANOG, ALDH1A1, and ABCG2." (PMID 25797257, 2015). "Intriguingly, cancer stem cell-like cells are known to express high levels of all the forementioned FoxM1 downstream effectors including WNT, EMT, and Sox2." (PMID 26444992, 2015). "On the other hand, stem cell markers such as OCT4, SOX2, NANOG and GATA4 and cancer stem cell (CSC)–like markers including ALDH1A1, CD44 and CD133 were not upregulated." (PMID 25875914, 2015). "This complex binds to theLef1 binding site of the target genes and modulates their transcription.EpICD is known to occupy promoter region and positively regulate SOX2, OCT4 and NANOG which contributes to self-renewal and pluripotency of cancer cells." (PMID 26176230, 2015). "Inhibition of SNORD78 resulted in the downregulation of a series of stemness factors, such as Sox2 and Oct4, which has been shown to enhance NSCLC malignancy by inducing cancer stem cell-like properties and epithelial-mesenchymal-transition." (PMID 25975345, 2015). "As we have seen in other cancers and cancer cell lines, knockdown of DCLK1 reduced the expression of stem cell pluripotency factors MYC, NANOG, POU5F1/OCT4, and SOX2 in Caki-2 cells." (PMID 25605241, 2015). "However, targeting signals upstream or downstream of SOX2 may prove beneficial in cancer therapy." (PMID 25114775, 2014). "In this study, we used two genes, SOX2 and hTERC, which are considered potential OSCC marker genes, to evaluate the FISH/cytobrush technique a screening method for cancer cell detection in smears from the oral and oropharyngeal cavity." (PMID 24410919, 2014). "We observed that the protein expression of the TAM markers CD68 and CD163 as well as the cancer stem cell (CSC) markers ALDH1, CD44, and SOX2 increased successively from the normal oral mucosa to OSCC." (PMID 24883329, 2014). "siRNA-mediated knockdown of snoRA42 in CD133+ cells led to a significant decrease in transcript levels of the genes, including Oct4, Nanog, Sox2, Notch1, Smo, and ABCG2 compared to scrambled siRNA-treated CD133+ cancer cells." (PMID 24886050, 2014). "IR has been shown to reprogram differentiated cancer cells into iBCSCs or liver CSCs through the re-expression or upexpression of the stemness genes Oct4/SOX2/Nanog/KLF4 and SOX2/OCT3/Oct4, respectively." (PMID 25003837, 2014). "Similar to SOX4, SOX2 and SOX9 have also been shown to have tumor suppressive effects in specific cancer types (gastric cancer and melanoma, respectively), further emphasizing the context specific nature of SOX involvement in carcinogenesis." (PMID 25594027, 2014).
cancer (continued). "We therefore investigated the CpG methylation pattern of NANOG (also known as NANOG1), OCT4, SOX2, KLF4 and c-MYC in human cancer cell lines by bisulfite sequencing approach." (PMID 24023739, 2013). "FSH upregulated the expression of Notch, Sox2 and Nanog and these effects were abolished by knocking down OCT4, suggesting that several cancer stem cell pathways are involved in FSH regulation." (PMID 23921511, 2013). "Previous studies have demonstrated the activation of downstream targets of NANOG, OCT4, SOX2 and MYC genes in aggressively growing human cancers." (PMID 24023739, 2013). "It has been demonstrated that OCT4, SOX2, c-MYC, LIN28, NANOG and KLF4 are required for ESC self-renewal and pluripotency and are upregulated in some aggressive cancers and in CSCs." (PMID 24040120, 2013). "Our results revealed further cancer-relevant target genes including STAG2, CNOT6, SOX2, CDC25A and SFRS3." (PMID 23358700, 2013). "SOX2 and ALDH1 were highly expressed in AT and CL, and both of these genes are putative cancer stem cell markers because of their contributions to self-renewal and a pleuripotent phenotype." (PMID 23451093, 2013). "Taken together, SOX2 and the other SOX family members activate the expression of MYC and CCND1, perhaps bypassing the blocked ER-mediated mitogenesis by which cancer cell proliferation can be maintained." (PMID 24355041, 2013). "The detection of AAbs to some antigens was, however, more specific for the detection of certain cancer subtypes; for example, MAGE A4 predicted the presence of NSCLC more often than SCLC, while the reverse was true for HuD and SOX2." (PMID 22492236, 2012). "In CSCs from various cancers, there is expression of the key ‘stemness’ genes, Oct-4, Bmi1, Notch1, ALDH1, and Sox2." (PMID 22662215, 2012). "Through enrichment analysis of SOX2 target genes in the cell signaling pathway database of Kyoto Encyclopedia of Genes and Genomes (KEGG), we found the pathway in cancer is one of the most significantly enriched ones." (PMID 22615765, 2012). "In this study, we found that down regulation of Sox2 and Oct3/4 in HepG2 or Huh7 cells was associated with lower resistance to gamma radiation in a clonogenic survival assay which allows for the survival and proliferation of non-stem cancer cells as well as CSCs." (PMID 22928007, 2012). "Like SOX2, Brachyury is an important gene in embryonic development and induces EMT in early embryonic stages and in cancer cells." (PMID 23076115, 2012). "We also found that short-term telomerase inhibition results in decreased expression of genes, such as OCT3/4, NANOG, SOX2, and BMI1, that regulate normal and cancer stem cells." (PMID 20824134, 2010). "Given the role of SOX2 in the control of normal embryonic and neural SCs homeostases and our identification of SOX2 as a novel oncogene in lung SCC, it will be of interest to dissect its involvement in cancer stem cells (CSCs) isolated from squamous tumors." (PMID 20126410, 2010). "Network analysis pinpointed specific regulatory hubs, such as SOX2 and SERPINE1 for HPV16, and ERBB4 and GLI1 for HPV18, which may facilitate malignant tumor growth by disrupting metabolic, keratinization, and extracellular matrix pathways." (PMID 41993883, 2026). "Immunohistochemical analysis further revealed a significant decrease in Ki-67, Slug and SOX2 expression, accompanied by an increase in E-cadherin levels, suggesting a reversal of EMT coupled with attenuation of cancer cell stemness and reduced proliferative activity." (PMID 41522354, 2026). "SOX2 contributes to the up-regulation of CSC expression and promotes cancer cell invasion through mechanisms including EMT, anti-apoptotic pathways or pro-survival signaling cascades, ATP-binding cassette-like drug transporters, lineage plasticity, and evasion of immune surveillance." (PMID 39976818, 2025).
cancer (continued). "Crucial stemness genes such as KLF4, OCT-4, SOX2, NANOG, and C-MYC, which are important regulators of pluripotency and the capacity for self-renewal in CSCs, were expressed in cancer cells exposed to 5-FU in comparison to both spheroids and their parental population." (PMID 40251609, 2025). "It's our study come up with that propofol could inhibit cancer cell stemness and proliferation by regulation of FOXO3/SOX2 axis firstly." (PMID 39991565, 2025). "OCT4, KLF4, SOX2, c‐MYC and other stem cell reprogramming factors play key roles in inducing stem cell formation, and many studies have shown that they can also promote the occurrence of CSCs in cancer and up‐regulate the expression of CSC markers." (PMID 40717222, 2025). "In addition to c-MYC, other pluripotency factors such as OCT4, SOX2, NANOG, and KLF4 are known to act as potent cancer drivers." (PMID 40541178, 2025). "Conversely, SOX2 and POU5F1 expression levels progressively increased with advancing cancer stage." (PMID 40279337, 2025). "The differential expression of SOX2, PIWI proteins, and MALAT1 between cancer patients and healthy controls supports their potential utility as plasma-based biomarkers for distinguishing cancer cases from non-cancer cases." (PMID 40674376, 2025). "Furthermore, treatment of TNBC cells including the parental MDA-MB-231, MDA-MB-468, and Hs578T, with 231-RR-EVs led to increased expressions of active β-catenin, as well as other cancer stemness proteins including c-Myc, OCT4, and SOX2." (PMID 40657369, 2025). "SOX2 is one of the members of the SOX transcription factor family, which is believed to be an important transcription factor that plays a role in embryonic development, maintenance of stem cells, cancer progression, and resistance to cancer treatment." (PMID 39976818, 2025). "OCT4 (POU5F1), SOX2, and NANOG were expressed at higher levels in cancer cell lines than in MSCs." (PMID 39621192, 2025). "Investigating the molecular pathways involving SOX2, PIWI proteins, and MALAT1 could provide deeper insights into their role in cancer progression, potentially paving the way for targeted therapeutic strategies." (PMID 40674376, 2025). "Moreover, we found that AKT-SOX2 axis is a modulator of cancer stemness and chemoresistance and developed a combination strategy using an AKT inhibitor to decrease SOX2 protein level and enhance OS sensitivity to chemotherapeutic drugs." (PMID 39994220, 2025). "Further, SOX2, KLF4 and c-MYC are particularly important in regulating migration and invasion, often through pathways related to EMT, with implications in both development and cancer metastasis." (PMID 40019880, 2025). "Besides, in SCC cells, TGF-β can activate the AKT pathway, followed by overexpression of SOX2 and ABCG2, which are characteristic of cancer stem cells, indicating the ability to induce cancer cell dedifferentiation that corresponds to cisplatin resistance." (PMID 40486962, 2025). "Nonetheless, in the case of LUSC, SOX2 expression frequently coincides with amplifications at its chromosomal locus, and has been described as a lineage-survival factor rather than a cancer stem cell marker." (PMID 40676628, 2025). "Further research has highlighted the key roles of TFs, SOX2, and SOX9, in defining the identity of latency-competent cancer (LCC) cells, with differential expressions impacting the epigenetic landscape and transcriptional activity across lung and breast cancer BrM models." (PMID 40016470, 2025). "In addition to cancer cell progression, they also investigated the stemness of cancer cells by measuring pluripotent transcription factors (OCT4, Nanog, SOX2, ALDH1A1)." (PMID 40126346, 2025). "FOXA1 is a key marker that helps distinguish the luminal subtype from the Ba/Sq subtype of UC tumors, and SOX2 is known to be a negative upstream regulator of FOXA1 expression in different cancers." (PMID 40643470, 2025).